POLR2L (RNA polymerase II, I and III subunit L)
Description:
DNA-dependent RNA polymerase catalyzes the transcription of DNA into RNA using the four ribonucleoside triphosphates as substrates. Common component of RNA polymerases I, II and III which synthesize ribosomal RNA precursors, mRNA precursors and many functional non-coding RNAs, and a small RNAs, such as 5S rRNA and tRNAs, respectively.
Synonyms: RPB7.6; RPB10beta; RBP10; RPABC5; hRPB7.6; hsRPB10b; RPB10
Tractability: Small molecule: a structure with a bound ligand is known. PROTAC: ubiquitination databases record sites on it; its protein half-life has been measured.
Gene: Protein-coding gene on chromosome 11 (837,356 to 842,561, reverse strand). Ensembl gene ENSG00000177700.
Subcellular location: Nucleus; Nucleus, nucleolus
Subcellular location (Human Protein Atlas): Nucleoplasm
Pathways (Reactome):
Gene expression (Transcription): B-WICH complex positively regulates rRNA expression; Formation of RNA Pol II elongation complex; Formation of the Early Elongation Complex; MicroRNA (miRNA) biogenesis; NoRC negatively regulates rRNA expression; PIWI-interacting RNA (piRNA) biogenesis; RNA Pol II CTD phosphorylation and interaction with CE; RNA Polymerase I Promoter Escape; RNA Polymerase I Transcription Initiation; RNA Polymerase I Transcription Termination; RNA Polymerase II Pre-transcription Events; RNA Polymerase II Promoter Escape; RNA Polymerase II Transcription Elongation; RNA Polymerase II Transcription Initiation; RNA Polymerase II Transcription Initiation And Promoter Clearance; RNA Polymerase II Transcription Pre-Initiation And Promoter Opening; RNA Polymerase III Abortive And Retractive Initiation; RNA Polymerase III Chain Elongation; RNA Polymerase III Transcription Initiation From Type 1 Promoter; RNA Polymerase III Transcription Initiation From Type 2 Promoter; RNA Polymerase III Transcription Initiation From Type 3 Promoter; RNA Polymerase III Transcription Termination; RNA polymerase II transcribes snRNA genes; Transcriptional regulation by small RNAs
Disease: Abortive elongation of HIV-1 transcript in the absence of Tat; Dengue Virus-Host Interactions; Formation of HIV elongation complex in the absence of HIV Tat; Formation of HIV-1 elongation complex containing HIV-1 Tat; Formation of the HIV-1 Early Elongation Complex; HIV Transcription Initiation; HIV elongation arrest and recovery; Pausing and recovery of HIV elongation; Pausing and recovery of Tat-mediated HIV elongation; RNA Pol II CTD phosphorylation and interaction with CE during HIV infection; RNA Polymerase II HIV Promoter Escape; Signaling by FGFR2 IIIa TM; Tat-mediated HIV elongation arrest and recovery; Tat-mediated elongation of the HIV-1 transcript; Transcription of the HIV genome
and 15 more pathways
Gene Ontology:
Molecular function: protein binding; zinc ion binding; DNA-directed RNA polymerase activity; DNA binding
Biological process: termination of RNA polymerase III transcription; transcription by RNA polymerase II; transcription by RNA polymerase III; transcription elongation by RNA polymerase I; transcription elongation by RNA polymerase II; transcription initiation at RNA polymerase II promoter; transcription initiation at RNA polymerase III promoter; nucleolar large rRNA transcription by RNA polymerase I; regulation of transcription by RNA polymerase I; termination of RNA polymerase I transcription; transcription by RNA polymerase I; transcription initiation at RNA polymerase I promoter; tRNA transcription by RNA polymerase III; DNA-templated transcription
Cellular component: nucleoplasm; nucleus; RNA polymerase I complex; RNA polymerase II, core complex; RNA polymerase III complex; cytosol; nucleolus
Genetic constraint (gnomAD): Loss-of-function variants: 5 observed, 4.42 expected, observed/expected ratio (o/e) 1.13, 90% interval 0.57 to 1.87. That is too few expected variants to judge how well the gene tolerates losing a copy. Missense variants: 93 observed, 77.26 expected, observed/expected ratio (o/e) 1.2, 90% interval 1.02 to 1.43. Synonymous variants: 59 observed, 37.25 expected, observed/expected ratio (o/e) 1.58, 90% interval 1.28 to 1.9.
Homologues: Orthologues: chimpanzee POLR2L (100% identical), dog POLR2L (100% identical), guinea pig POLR2L (100% identical), mouse Polr2l (100% identical), tropical clawed frog polr2l (100% identical), zebrafish polr2l (99% identical), rat Polr2l (96% identical), Drosophila melanogaster Polr2L (93% identical), rat Polr2sl1 (88% identical), Caenorhabditis elegans rpb-10 (85% identical). Paralogues in human: RPL32 (27% identical).
Diseases named in the same sentence as POLR2L in open-access papers:
POLR2L is named in the same sentence as 11 diseases in open-access papers, as found by Europe PMC text mining. Sharing a sentence is not in itself a finding about the gene and the disease. The quoted sentences say what the papers report.
COVID-19 (2 papers, 2022 to 2023). A disease caused by infection with severe acute respiratory syndrome coronavirus 2. "When analyzing the DEGs using the bioinformatic platform Enrichr-KG, the most relevant transcription factors potentially driving the differences in kidney gene expression between COVID-19 AKI and non-COVID-19 AKI were POLR2L, EIF3K, BOLA3, RFXANK, and ZNF576." (PMID 38003268, 2023). "In the present study, four risk regulators (UBTF, POLR2L, YBX1 and YPEL2) were identified to be associated with COVID-19 severity." (PMID 35139909, 2022).
glioma (2 papers, 2021 to 2024). A benign or malignant brain and spinal cord tumor that arises from glial cells (astrocytes, oligodendrocytes, ependymal cells). "The gene POLR2L, regulated by oCGI Chr11:728884-729383 in our study, played a significant role in cell communication in C2 glioma cells, although it was not the most significantly activated gene." (PMID 39391717, 2024).
gastric cancer (1 paper, 2023). A primary or metastatic malignant neoplasm involving the stomach. "The POLR2L gene encodes a subunit of RNA polymerase II, which was the main upregulated gene of drug resistance in gastric cancer found in a screening of the TCGA database." (PMID 36901944, 2023).
lung carcinoma (1 paper, 2019). "POLR2L, a subunit of RNA polymerase II, was found to be a prognostic splicing factor, and its AS was also prognostic in lung cancer." (PMID 31729991, 2019).
prostate carcinoma (1 paper, 2024). A carcinoma that arises from epithelial cells of the prostate gland. "The high contributions of POLR2L to the transcriptomic alteration in all three types of thyroid cancer samples, as measured with the Transcriptomic Distance, indicate that it might be a good target for anti-thyroid cancer gene therapy, as was suggested for prostate cancer." (PMID 38790250, 2024).
Sepsis (1 paper, 2022). Sepsis is defined as life-threatening organ dysfunction caused by a dysregulated host response to infection. "POLR2J and POLR2L are associated with purine metabolism and pyrimidine metabolism in sepsis patients." (PMID 35265105, 2022). "In the present study, we also identified POLR2J and POLR2L as two of the hub genes of sepsis, indicating the important role of these two metabolism-related genes in the pathophysiology of sepsis." (PMID 35265105, 2022). "Meanwhile, the present study identified eight metabolism-related genes (NME1, NME6, POLD4, POLE4, POLR2J, POLR2L, ADCY3, and ENTPD1) in patients with sepsis and the identified metabolism-related genes may represent diagnostic and therapeutic biomarkers of sepsis." (PMID 35265105, 2022).
thyroid cancer (1 paper, 2024). "The differences between the tumor and the cell cultures indicate that, although POLR2L is a major player in the development of several forms of thyroid cancers, the involved molecular mechanisms are distinct." (PMID 38790250, 2024).
tumor (7 papers, 2019 to 2024). "The scatter plots illustrated that DCK and POLR2L in the signature were significantly associated with tumor immune microenvironment through single cell analysis based on GSE140228, GSE98638, GSE146115, GSE146409, GSE166635, GSE179795." (PMID 38517376, 2024). "To explore the regulatory role of oCGIs in the tumor center and periphery, we focused on the common downstream target in cell communication between the two niches, namely the POLR2L gene, for subsequent validation." (PMID 39391717, 2024). "As the POLR2L gene plays a crucial role in cell communication between tumor cells and other components of the tumor microenvironment, we selected oCGI (Chr11:728884-729383) and its target, POLR2L gene, for validation." (PMID 39391717, 2024). "The results revealed that the expression of prognostic genes was significantly higher in tumor grades 3–4 than in tumor grades 1–2, except for POLR2L and PPP2R5B (P < 0.05)." (PMID 37923899, 2023). "The gene expression profiles suggested that the expression levels of CDC20, UQCRH, TIMM10, TIMM13, POLR2L, and NDUFAB1 were upregulated in tumor tissue." (PMID 36901944, 2023).
cancer (5 papers, 2021 to 2024). A tumor composed of atypical neoplastic, often pleomorphic cells that invade other tissues. "For instance, higher levels of CHD1L, HDAC1, MUTYH, NEIL3, POLR2L, RUVBL1, and SPP1 expression in cancer cells have been linked to higher levels of drug resistance to nelarabine, acridine, chlorambucil, dexrazoxane, cladribine, and other drugs." (PMID 37923899, 2023). "By the most comprehensive measure (Transcriptomic Distance, TD), POLR2L had the largest contribution to the overall cancer-induced transcriptomic alteration within this gene subset in T (TD(T) = 145, TD(Φ) = 497, TD(Θ) = 495) and GTF2I in both cell lines (TD(T) = 45, TD(Φ) = 964 TD(Θ) = 872)." (PMID 38790250, 2024). "By contrast, some other genes encoding the polymerase II subunits were characterized by higher methylation in carcinomas than in BOTS (e.g., promoters and/or first exons of POLR2G and POLR2L, as well as the distal promoter of POLR2C, and the cds of POLR2E, GR file)." (PMID 39456618, 2024).
POLR2L also shares sentences with these, for which no sentence is quoted: non-small cell lung carcinoma (1 paper); sarcopenia (1).